TNC (tenascin C)
Diseases named in the same sentence as TNC in open-access papers (continued):
Sharing a sentence is not in itself a finding about the gene and the disease.
cancer (continued). "Various cell types, including fibroblasts, endothelial cells, immune cells, and cancer cells, express tenascin-C during embryonic development and tissue repair processes." (PMID 40699873, 2025). "Tenascin-C (TNC) is an extracellular matrix glycoprotein widely and abundantly expressed in the cancer stroma." (PMID 40046232, 2025). "This functional versatility and its inducible expression have positioned TNC as a key molecule in the research on various diseases, including cardiac disease, rheumatic diseases, and multiple types of cancers." (PMID 40981103, 2025). "In contrast, Oct4 transactivates TNC in an Sp1-independent manner, thereby promoting cancer metastasis." (PMID 40981103, 2025). "Similar to oncofoetal fibronectin, tenascin C expression is intensely studied in pathologies, including cancer." (PMID 41009413, 2025). "For example, in cancer, TNC exhibits a dual role in the regulation of cell adhesion and proliferation." (PMID 40981103, 2025). "The inhibitory role of tenascin-C released by tumor cells was found in many other cancer types, including prostate cancer, lung cancer, breast cancer, bladder cancer, pancreatic cancer, and colorectal cancer." (PMID 41294803, 2025). "One of the extracellular matrix proteins, tenascin-C (TN-C), is known to be upregulated in age-related inflammatory diseases such as cancer and cardiovascular diseases." (PMID 38339104, 2024). "Because a similar observation was observed in other cancers, investigators suggest that exons 14 and 16 of Tenascin-C be considered as markers of prognosis and invasion in various cancers." (PMID 39796135, 2024). "This revealed an overall increased deposition by AFs of collagen family members (COLs, including COL4A1 and COL11A1), fibrillins (FBN1 and 2) and tenascin (TNC), previously involved in lung fibrosis and deposited by CAFs in other cancers." (PMID 37938546, 2023). "Network analysis identified a key role of mesothelial cells, which communicated with cancer cells by TNC and LIF, and distinct immune cells, including all subtypes of DCs, macrophages, and monocytes by ICAM1." (PMID 37649596, 2023). "In the current study, upregulated expression of tenascin-C in cancer cells was correlated with the outcome of patients who had stage 2 or 3 CRC." (PMID 36222933, 2023). "TNC has also been associated with epithelial-mesenchymal transition (EMT), a process linked to increased cancer cell motility and invasiveness." (PMID 37759229, 2023). "In melanoma, TGFBI hinders cell adhesion to fibronectin, collagen-I, and laminin whereas co-localized with fibrillar fibronectin/TNC/periostin structures which favors invasive state of cancer." (PMID 36906534, 2023). "The excessive and persistent accumulation of tenascin-c has been observed in various chronic pathological conditions, such as cancer and fibrosis." (PMID 37887075, 2023). "LYZ is associated with neutrophil degranulation and host defense peptides, whereas COL1A1, COL1A2 along with HGF, TNC, and VEGFA are all part of the PI3K pathway, which plays an important role in cancer progression, and has been implicated in TNT regulation." (PMID 37955637, 2023). "While chemokines and tenascin-C have been individually described as pivotal players in cancer, inflammation, and other pathological conditions, little is known about how their interplay affects each other’s function and thus disease progression." (PMID 37834140, 2023). "Using comprehensive analyses, we found that the expression of specific mRNAs, including tenascin-C, SPP, and laminin in cancer cells, and OR11H members in CAFs is closely associated with cancer metastasis." (PMID 36222933, 2023). "TNC, MMPs, and FN stimulate cancer cell invasion and serve as ECM targets for radionuclide interventions." (PMID 35788730, 2022). "Tenascin-C expression can be induced in cancer cells as well as in stromal cells by different factors, including EGF, TGF-β, b-FGF and TNF-α." (PMID 35008401, 2022).
cancer (continued). "TNC is recognized as a promoter of cancer progression in numerous malignancies and is expressed in highly aggressive cancer cells." (PMID 35469015, 2022). "In adults, tenascin-C expression can be upregulated by mechanical stress, upon tissue repair or in cancer." (PMID 35008401, 2022). "TNC is a matricellular protein, which is expressed during embryogenesis, cancer and various remodelling processes." (PMID 35137102, 2022). "Although the expression of tenascin-C in the adult tissue is usually low, it has been described to be elevated in many human cancers." (PMID 35008401, 2022). "SMOC1 is a calcium-dependent conformational glycoprotein and a true basement membrane component, which has been suggested to be a new cancer-related protein and has been shown to interact with TNC in vitro." (PMID 36292695, 2022). "On the other hand, TNC is a hexameric glycoprotein that has been recently attributed to cancer growth." (PMID 36289644, 2022). "Dual effects of TnC have also been reported regarding cell proliferation as it has been known to promote proliferation in cancer tissues, but sustain or inhibit it in fibroblasts." (PMID 36092707, 2022). "Tenascin-C has been found to induce and activate others signaling pathways in cancer cells such as JNK, Wnt, Notch, AKT/HIF1α and TGF-β." (PMID 35008401, 2022). "Specific conditions induce persistent tenascin-C production, such as infection, inflammation, wound-healing processes, cancer, autoimmune and fibrotic diseases." (PMID 36294311, 2022). "Different binding partners of TNC have been so far identified and, depending on the specific cancer cell type, the interaction of TNC with its receptor induces cell proliferation, adhesion, invasion, and angiogenesis and escape from immune surveillance." (PMID 35056924, 2021). "Attention will be paid to Tenascin-C, a matrix glycoprotein commonly upregulated during cancer that participates to PDAC progression and thus contributes to poor prognosis." (PMID 33889150, 2021). "Short TNC isoforms are known to promote cell attachment and differentiation, while long isoforms are expressed during organogenesis or in cancer, and promote cell migration and proliferation." (PMID 34777012, 2021). "TNC was mainly distributed in cytoplasm and extracellular matrix and was significantly upregulated in cancer tissues than in normal tissues." (PMID 34588421, 2021). "When the cancer EVs were applied to the fibroblasts directly, the effects on tenascin-C expression were similar to those of the conditioned medium, and the fibroblast activation markers α-SMA and periostin were also upregulated." (PMID 34564696, 2021). "Tenascin-C (TNC) is an extracellular matrix molecule that drives the progression of many types of human cancer." (PMID 34490089, 2021). "TNC is a glycoprotein of the ECM and frequently associated with cancer, including metastasis initiation and EMT." (PMID 34592589, 2021). "Two key matricellular proteins, well studied for their roles in cancer progression, namely, tenascin C and periostin, were shown to be significantly reduced at both the mRNA and protein levels following hVDAC1 depletion." (PMID 34200480, 2021). "We also assessed the top genes differently expressed between penta- and tetra-cultures, where we identified several ECM molecules previously associated with poor prognosis in cancer (COL11A1, TNC, TGFβ1)." (PMID 34189439, 2021). "Enhanced levels of many cancer-related proteins are found in the CM of ET-1-treated cells, including MMPs, Snail, Tenascin-C, Vimentin, and downregulated levels of E-cadherin." (PMID 34926453, 2021). "Tenascin C (TNC) is a gene belonging to a family of extracellular matrix (ECM) glycoproteins that is known to be overexpressed in cancer cells." (PMID 32064050, 2020). "Tenascin-C is abundant in the extracellular matrix of cancers of the breast, colon, pancreas, prostate, uterus, lung, skin, and brain, to name a few." (PMID 33692777, 2020).
cancer (continued). "High TNC levels are correlated with poor prognosis in patients with various types of cancer, and its expression is therefore considered a poor prognostic factor." (PMID 32708610, 2020). "ECM molecules like Fibulin-3, Tenascin-C and Emilin-2 have been known to associate with growth factor receptors like EGFR to regulate its activation and function during cancer progression." (PMID 32719793, 2020). "TNC is re-expressed in reactive stroma in human cancers, and there is evidence of its expression in low-grade tumors (Gleason 3) of human PCa and, possibly, already activated at the prostatic intraepithelial neoplasia (PIN) stage." (PMID 33334054, 2020). "In contrast, TNC is specifically and transiently expressed upon pathological conditions such as inflammation, fibrosis, and cancer." (PMID 33335533, 2020). "Based on these activities, TNIIIA2-containing TNC fragments/peptides are involved in the acquisition of aggressiveness in cancer progression." (PMID 32708610, 2020). "Here Tenascin-C acts in an autocrine manner on disseminated cancer cells to support their self-renewal, survival and lung colonization characteristics." (PMID 33014869, 2020). "Tenascin-C (TNC) is an extracellular matrix protein that is widely expressed in the stromal fibroblasts of various cancers." (PMID 32322169, 2020). "So, this integrin possibly, in conjunction with growth factor receptors, can regulate proliferation and migration of cancer cells influenced by tenascin-C protein." (PMID 32340328, 2020). "Elevated TNC expression was reported to predict poor prognosis among patients with various cancers, and TNC can be a serum biochemical marker for cancer." (PMID 33101302, 2020). "Although there have been fewer reports on TNX expression in cancer compared with reports on the expression of TNC and TNW in cancer, reports on TNX expression have been increasing." (PMID 33335533, 2020). "Tenascin-C has been proposed as a marker, immunotherapy target and indicator of prognosis in many kinds of cancer, but its use has been limited by its presence, albeit at lower levels, in many normal adult tissues." (PMID 33692777, 2020). "Taken together, Tenascin-C appears to play a role in metastatic colonization at multiple sites, both those naturally rich in Tenascin-C and also in tissues that are activated to upregulate Tenascin-C in response to the presence of cancer cells." (PMID 33014869, 2020). "Tenascin-C (TNC), an ECM glycoprotein associated with poor prognosis cancer, also plays a role in the regulation of T-cell infiltration in cancer." (PMID 33187209, 2020). "These authors revealed that expression of tenascin-C in ESCC cells is directly associated with that of SRY-box transcription factor 2 (SOX2), a well-known cancer stem cell marker." (PMID 32079295, 2020). "Short TNC isoforms promote cell attachment, cell differentiation and the formation of focal adhesions, whereas long TNC isoforms promote cell migration and are expressed when morphogenesis is very active, like in embryogenesis or cancer growth." (PMID 32198404, 2020). "A recent study reported that the up-regulation of TNC is a poor prognostic marker and can promote cancer cell migration." (PMID 31722693, 2019). "Next to collagens, tenascin C is another remarkable cancer cell-derived ECM component overexpressed upon MG stress." (PMID 30674353, 2019). "Integrin family members, including integrins α9β1, αvβ1, α5β1, and αvβ3,8 are crucial receptors of TNC that regulate matrix-cell interactions in the cancer microenvironment." (PMID 31649319, 2019). "MMP-3 damages the extracellular matrix inhibitor, deactivates several proteinase inhibitors and increases the proliferation of cancer cells through fibrosis, neovascularization, and tenascin-C expression." (PMID 31372176, 2019). "tenascin-C (TNC) is one of the other ECM glycoproteins that drives the progression of many types of human cancer." (PMID 31807240, 2019).
cancer (continued). "Tenascin-C (TNC), an extracellular matrix glycoprotein, has been implicated in progression of various types of cancer." (PMID 30633201, 2019). "Tenascin-C is readily expressed in certain healthy tissues and it is well established that it can be re-expressed under pathological conditions other than cancers, such as inflammation, healing wounds, infections, and asthma." (PMID 31032255, 2019). "Non-structural ECM proteins known as matricellular proteins, such as tenascin C and periostin are also expressed by CAFs, and their effects on cancer development has widely been reported." (PMID 31137693, 2019). "The high expression of TNC correlates with poor prognosis in several cancer types, including breast cancer, glioblastoma and colorectal cancer." (PMID 31036754, 2019). "While tenascin-C and tenascin-W are often co-expressed in the stroma of various solid tumors, certain cancers selectively express only one of the two extracellular matrix proteins." (PMID 31032255, 2019). "This contrasts with tenascin-C, which can be expressed by stromal as well as cancer cells (e.g., in gliomas)." (PMID 31032255, 2019). "Tenatumomab conjugated with 131I has been developed for RIT applications, and it is currently in phase I clinical development in tenascin-C expressing cancer (NCT02602067)." (PMID 29515769, 2018). "Considering the advances regarding functional roles for TnC and TnI, it seems likely that TnT is also involved in cancer cell growth and migration." (PMID 29416706, 2018). "For instance, deregulated expression of tenascin-C (TNC), which is one of the ECM proteins in stem cell niche, has been associated with their roles in cancer progression such as angiogenesis, invasion and metastasis." (PMID 29506506, 2018). "Given the inherent Ca2+-binding properties of TnC, a link between calcium signaling and TnC in cancer cells is conceivable." (PMID 29416706, 2018). "Inhibition of JNK activity provides an opportunity to repress simultaneously the expression of SPP1 and TNC in the cancer cells." (PMID 30190333, 2018). "The first glimpse of mechanistic insight into the role of TnC in cancer emanated from a study on the metastatic potential of human ovarian cancer." (PMID 29416706, 2018). "Identification of the niche matrix components SPP1 and TNC as relevant mediators of therapy resistance highlights the significance of the ECM as a valuable source of cancer targets." (PMID 30190333, 2018). "This self-feedback loop can explain the transient high expression of tenascin-C in acute inflammation and persistently high expression of tenascin-C in chronic inflammation and cancer." (PMID 30442110, 2018). "Tenatumomab has been directly conjugated with 131I for RIT application and is currently in phase I clinical development in tenascin-C expressing cancer (NCT02602067)." (PMID 29515769, 2018). "First, we examined coexpression of key component of the PFL; Twist1, Prrx1, and TNC in clinical samples such as patient tissue-derived ex vivo cultured CAFs, archived paraffin-embedded cancer tissues, and TCGA data." (PMID 30069061, 2018). "We describe a novel association between NRP-1 and TNC expression, an extracellular matrix (ECM) glycoprotein molecule that induces EMT, migration, proliferation and immune modulations in cancer." (PMID 29728077, 2018). "Characteristic fibroblast activation gene targets such as ACTA2, COL1A1 and TNC were significantly upregulated in CAFs together with typical cancer-induced chemokines most prominently CXCL12, which has been reported for this cell line." (PMID 28372546, 2017). "Our large cohort study using TCGA datasets indicated that the expression levels of ITGA3, ITGA6, and TNC were upregulated in cancer tissues." (PMID 28415821, 2017).
cancer (continued). "Cancer cells and corresponding stromal cells also exhibit TNC expression, and high expression of TNC has been reported in several cancers." (PMID 28415821, 2017). "The extracellular matrix (ECM) molecule tenascin C (TNC) is known to be highly expressed under various pathological conditions such as inflammation and cancer." (PMID 28106752, 2017). "Several studies have demonstrated that TNC binds directly to integrins, and TNC/integrin-mediated signalling contributes to embryonic development, tissue repair, and cancer pathogenesis." (PMID 28415821, 2017). "Knockdown assays using siRNAs showed that ITGA3, ITGA6 and TNC acted as cancer promoting genes in HNSCC cells." (PMID 28415821, 2017). "Among 5 genes, we focused on ITGA3, ITGA6, and TNC genes because aberrant integrin-mediated signalling promoted cancer cell aggressiveness according to our previous studies." (PMID 28415821, 2017). "It has been reported that the expression of TNC is correlated with the malignant potential of cancer." (PMID 28106752, 2017). "Especially, patients with Tenascin-C expression in both cancer cells and stromal fibroblasts showed apparently reduced OS and DFS rates." (PMID 26731558, 2016). "Tenascin-C expression was observed more frequently in stromal fibroblasts (94/136, 69.1%) than in cancer cells (75/136, 55.1%) from patients with ESCC." (PMID 26731558, 2016). "QD-MUC-1 showed relatively higher fluorescence signals in the membrane of C6 and HeLa cell lines than other cancer cells, as nucleolin, tenascin-C, and mucin proteins had different cellular expression in different cancers." (PMID 27973403, 2016). "Functionally, Tenascin-C interacts with fibronectin and can be defined as an anti-adhesive or adhesion-modulating protein; Tenascin-C increases the invasive and metastasis potential of malignant tumors." (PMID 26731558, 2016). "We divided the patients into the following groups to determine the clinical significance of Tenascin-C expression: those who showed Tenascin-C expression in cancer cells and those who showed Tenascin-C expression in stromal fibroblasts." (PMID 26731558, 2016). "The results of the survival analysis showed that overexpression of Tenascin-C in ESCC cancer cells as well as in stromal fibroblasts was an independent poor prognostic factor of both OS and DFS." (PMID 26731558, 2016). "Tenascin-C expression was found in both, stromal and cancer cells and has a direct influence on epithelia-mesenchymal transition." (PMID 26967391, 2016). "In this study, we found that overexpression of Tenascin-C in stromal fibroblasts and cancer cells was an independent predictor of poor prognosis in ESCC patients." (PMID 26731558, 2016). "Positive signals of Tenascin-C expression were localized mainly in the cytoplasm of cancer cells and stromal fibroblasts." (PMID 26731558, 2016). "In the Cox proportional hazard regression model, Tenascin-C overexpression in cancer cells and stromal fibroblasts was a significant independent hazard factor for OS and DFS in ESCC patients in both univariate and multivariate analyses." (PMID 26731558, 2016). "Because cancer tissues contain both cancer and stromal cells, we next determined the protein isoform profiles of Tenascin-C in each cell type." (PMID 26731558, 2016). "This is in addition to altered Tenascin-C (TNC) a well known matrix component of cancer-reactive and fibrotic stroma indicating such changes are likely valid." (PMID 26934553, 2016). "Elevated serum levels make tenascin C suitable for clinical monitoring of the most common cancer types." (PMID 26539408, 2015). "Tenascin-C (TNC) is associated with cellular injury and inflammation, and has many cellular functions, with roles in embryogenesis, wound healing and cancer progression." (PMID 26092119, 2015). "Stromal fibroblasts, in turn, remodel the ECM by secreting large amounts of collagen types I and III, tenascin C (TNC), and MMPs, and they create tracks for collective migration of cancer cells." (PMID 28536400, 2015).